IFI44L (interferon induced protein 44 like)
Diseases named in the same sentence as IFI44L in open-access papers (continued):
Sharing a sentence is not in itself a finding about the gene and the disease.
autoimmune disease (11 papers, 2014 to 2024). A disorder resulting from loss of function or tissue destruction of an organ or multiple organs, arising from humoral or cellular immune responses of the individual to their own tissue constituents. "Meanwhile, IFI44L (interferon-induced protein 44-like) promoter undergoes DNA methylation in various autoimmune diseases." (PMID 38510251, 2024). "The results of our study suggest that aberrant DNA methylation of IFI44L is a common signature of autoimmune diseases." (PMID 31024609, 2019). "IFI44L has been found to upregulate in the gene profile of many autoimmune diseases besides SLE." (PMID 35592687, 2022). "The consistent hypomethylation of IFI44L in blood from patients with several autoimmune diseases, together with its overexpression, corroborates the validity of our finding and suggests that differential methylation of IFI44L may serve as shared biomarker across these diseases." (PMID 30947741, 2019). "In SIgAD patients with concomitant autoimmune diseases, decreased expression levels of genes related to the type I interferon (IFN) pathway, including IFIT1, MX1, IFI6, and IFI44L, were observed." (PMID 38474381, 2024). "Another example is interferon induced protein 44 like (IFI44L), which is involved in the immune response to infection and autoimmune disorders and whose isoform expression has also been found to be clinically relevant." (PMID 35840341, 2022). "IFI44L, RADS2, and IFIT1 showed the highest fold changes and comparable increases in expression in active and inactive SLE patients; IFI44L is noteworthy as it has been reported to be predictive of SLE status relative to healthy controls and other autoimmune diseases." (PMID 34946847, 2021). "Our previous studies were the first to find abnormal expression of IFI44L in SLE peripheral blood and overexpression of IFI44L was most significant in SLE rather than other autoimmune diseases, which provided a new idea for disclosing the pathogenesis of SLE." (PMID 35592687, 2022). "Our integrated analysis also found that IFI44L, another type I IFN-related gene, is significantly hypomethylated in autoimmune diseases, although it was not annotated by GO in type I IFN-associated terms." (PMID 31024609, 2019).
hepatocellular carcinoma (10 papers, 2018 to 2024). A malignant tumor that arises from hepatocytes. "IFI44L serves as a tumor suppressor in hepatocellular carcinoma; in hepatocellular carcinoma patients, low IFI44L expression is associated with tumor size, recurrence, advanced stage and poor clinical survival." (PMID 34903206, 2021). "A previous study found that overexpression of IFI44L decreased doxorubicin chemoresistance and was associated with the better survival of hepatocellular carcinoma patients." (PMID 31949544, 2019). "Downregulation of IFI44L is frequently observed in hepatocellular carcinoma (HCC) and is correlated with patient’s poor survival." (PMID 35455671, 2022). "IFI44L has been recognized as a novel tumor-suppressor gene in human hepatocellular carcinoma that regulates met/Src signaling to affect cancer stemness, metastasis, and drug resistance." (PMID 34903206, 2021). "Recent evidence suggests IFI44L as a novel tumor suppressor regulating cancer stemness and metastasis in hepatocellular carcinoma by modulating Met/Src signaling." (PMID 34516357, 2021). "Previous studies had suggested that IFI44L participates in tumor progression in certain cancers, including osteosarcoma and hepatocellular carcinoma." (PMID 35047409, 2021). "IFI44L (interferon induced protein 44 like) can affect cancer stemness, metastasis, and drug resistance in hepatocellular carcinoma (HCC)." (PMID 31321241, 2019). "A recently identified gene, IFI44L is present in various types of tumors, including pancreatic ductal adenocarcinoma (PDAC), laryngeal cancer, hepatocellular carcinoma (HCC), and lung cancer (LC)." (PMID 39737399, 2024). "Interferon-induced protein 44 like (IFI44L) is a tumor suppressor gene, which regulates the Met/SRC signaling pathway in hepatocellular carcinoma to affect cancer cell migration, lung metastasis, and drug resistance, and can be used as an ideal prognostic marker." (PMID 34384424, 2021).
primary Sjögren’s syndrome (7 papers, 2014 to 2024). "Finally, we examined this IRG signature (ISG15, SIGLEC1, STAT1 RSAD2, IFI27 and IFI44L) in peripheral blood mononuclear cells (PBMCs) collected from a smaller cohort of healthy controls, disease controls, AAV and primary Sjogren’s syndrome (pSS) patients." (PMID 33859290, 2021).
rheumatoid arthritis (6 papers, 2017 to 2024). A chronic, systemic autoimmune disorder characterized by inflammation in the synovial membranes and articular surfaces. "IFI44L genes play vital roles in inflammatory and immune pathway genes in periodontitis and rheumatoid arthritis." (PMID 35566100, 2022). "IFI44L is a crucial gene connecting rheumatoid arthritis and periodontitis." (PMID 35566100, 2022). "Different IFI44L methylation levels show significant differences between SLE patients and healthy controls or other immune diseases like rheumatoid arthritis (RA)." (PMID 39737399, 2024).
HIV-1 infection (5 papers, 2014 to 2025). The type species of lentivirus and the etiologic agent of acquired immunodeficiency syndrome (AIDS). "Cotransfection of the IFI44L promoter with an HIV-1 infection activated IFI44L promoter transcription." (PMID 34722780, 2021). "We found that HIV-1 infection induced the expression of a set of ISGs (RSAD2, ISG15, IFI44L, and IFI27) that remained upregulated during the chronic phase of HIV-1 infection." (PMID 39104769, 2024). "After HIV-1 infection, upregulation of a cluster of ISGs (RSAD2, ISG15, IFI44L, and IFI27), as compared to pre-SC, emerged and the expression of these ISGs remained high during the untreated course of infection." (PMID 39104769, 2024). "We observed an increase in the levels of various ISGs such as MX1, IFI44L, DDX58, RSAD2, and several of the IFITs, which have been shown to play an important role against HIV-1 infection in MDMs." (PMID 25170834, 2014). "In primary myeloid cells, both HIV-1 infection and the viral accessory protein Vpr have been shown to activate this pathway, resulting in increased STAT1 phosphorylation together with coordinated induction of ISG15, MX1, IFIT3/IFI44L, and OAS genes." (PMID 41226717, 2025).
Sepsis (4 papers, 2019 to 2026). Sepsis is defined as life-threatening organ dysfunction caused by a dysregulated host response to infection. "Prior scRNA‐seq findings revealed significant upregulation of ZBP1, XAF1, IFI44L and SOCS1 in B cells from sepsis patients that exhibit increased susceptibility to PANoptosis." (PMID 40600354, 2026). "Prior scRNA‐seq data showed pronounced upregulation of ZBP1, XAF1, IFI44L and SOCS1 in B cells from sepsis patients that displayed heightened PANoptosis sensitivity." (PMID 40600354, 2026). "Additionally, ZBP1, XAF1, IFI44L, SOCS1, and PARP14 were notably high in HighPANscore cells, aligning with our observations of upregulated expression of IFI44, IFIH1, IFIT1, IFIT2, and RSAD2 in lung tissues from sepsis-induced animal models." (PMID 38239341, 2023). "We identified 687 differentially expressed genes between ARDS and ARDS-HSCT (adjusted p-value < 0.01), including IFI44L, OAS3, LY6E, and SPATS2L that had increased expression in ARDS vs. ARDS-HSCT; these genes were not differentially expressed in sepsis vs sepsis-HSCT." (PMID 30665420, 2019).
influenza (3 papers, 2013 to 2024). An acute viral infection of the respiratory tract, occurring in isolated cases, in epidemics, or in pandemics; it is caused by serologically different strains of viruses (influenzaviruses) designated A, B, and C, has a 3-day incubation period, and usually lasts for 3 to 10 days. "The influenza group’s validation experiment showed significant differences in all six genes (IFI44L, IFI44, RSAD2, IFIT3, EIF2AK2, and IFI27)." (PMID 38601162, 2024). "They found that interferon-related genes such as RSAD2, LAMP3, IFI44L, and OAS1 were significantly differentially expressed in individuals with symptomatic RSV, influenza, or HRV infection." (PMID 24265599, 2013).
melanoma (3 papers, 2016 to 2024). A malignant, usually aggressive tumor composed of atypical, neoplastic melanocytes. "Up-regulation of IFI44L is associated with melanoma and prostate cancer while overexpression of NKX2-2 is associated with Ewing’s sarcoma and fibromatosis." (PMID 27144453, 2016). "We used mRNA expression of the type I IFN-responsive genes Ly6E, MX1, IFI44L and IFITM1 to determine the pre-treatment type I IFN score in the PBMCs from the melanoma patients in our study." (PMID 38967829, 2024). "In melanoma and non-melanoma skin cancer cells with CDKN2A mutated, IFI44L is also reported upregulated." (PMID 28881752, 2017).
nasopharyngeal carcinoma (3 papers, 2017 to 2024). A carcinoma arising from the nasopharyngeal epithelium. "IFI44L is reported upregulated in human nasopharyngeal carcinoma cells modulated through the downregulation of miR-9." (PMID 28881752, 2017). "Following the application of miR-9 inhibitors, IFI44L expression was downregulated, indicating that miR-9 can possibley target and regulate IFI44L, thus affecting the relationship between nasopharyngeal carcinoma (NPC) and inflammation." (PMID 39737399, 2024).
psoriasis (3 papers, 2019 to 2025). An autoimmune condition characterized by red, well-delineated plaques with silvery scales that are usually on the extensor surfaces and scalp. "For example, OAS1, OAS2, OAS3, and IFI44L appear to be down-regulated by etanercept in responders to treatment for psoriasis." (PMID 30665420, 2019). "In contrast, antiviral genes MX1, OAS3, and IFI44L were suppressed in γδ T cells in psoriasis, suggesting that these cells may be less primed to combat viral threats; alternatively, this finding could reflect an upregulation of these genes within the control group." (PMID 41181116, 2025). "ISG15, MX1, IFI44L, and IFI27 were the characteristic psoriasis genes found in suprabasal keratinocytes." (PMID 36172384, 2022). "ISG15, MX1, IFI44L, and IFI27 were the characteristic genes of psoriasis in suprabasal keratinocytes." (PMID 36172384, 2022).
ZIKV infection (3 papers, 2020 to 2025). "During ZIKV infection, MEL reduces expression of TNFα, MX1 and IFI44L but significantly increases expression of IL-1β and IFNβ." (PMID 40821819, 2025).
Aicardi-Goutières syndrome (2 papers, 2020 to 2021). "We next examined baseline gene expression (qPCR) of archetypal interferon stimulated genes (ISGs) IFI27, USP18, MX1, OASL, IRF7, and MX2, and those ISGs found highly expressed in PBMCs from the type 1 interferonopathy, Aicardi-Goutières syndrome (AGS) patients (IFI27, ISG15, IFI44L, and RSAD2)." (PMID 33746960, 2021).
autoimmune disorders (2 papers, 2016 to 2021). "IFI44L has been considered to play a role in inflammation, autoimmune disorders, and cancer." (PMID 34516357, 2021).
bacteremia (2 papers, 2024 to 2025). "This study aimed to evaluate the efficacy of two transcripts, IFI44L and PI3, in the early differentiation between SFTS virus (SFTSV) infection and bacterial sepsis, as well as in the prompt identification of severe cases during epidemic seasons." (PMID 39688402, 2025). "A two-gene signature comprising ADGRE1 and IFI44L demonstrated limited sensitivity for assigning young infants with UTI without bacteremia as having bacterial infection." (PMID 38732074, 2024).
bronchiolitis (2 papers, 2023 to 2026). Inflammation of the bronchioles characterized by swelling of the bronchioles and mucus accumulation. "IFI27, together with other genes that were differentially expressed, such as IFI44, OAS3, EPSTII, and IFI44L, are generally significantly up-regulated in whole blood from infants admitted to hospital with severe RSV-bronchiolitis." (PMID 36622786, 2023).
dengue (2 papers, 2021 to 2024). "IFI44L contributes to DENV infection due to low levels of type I IFN response showed in patients with severe dengue disease." (PMID 34347790, 2021).
gastric cancer (2 papers, 2019 to 2025). A primary or metastatic malignant neoplasm involving the stomach. "For HER2+ gastric cancer, the high expression of VIM, IFI44, IFI44L, IFIT2, IFIT3, ISG15, OAS1, or OASL was associated with worse overall survival (P < 0.05)." (PMID 31949544, 2019).
measles (2 papers, 2019 to 2022). A highly contagious viral infection caused by the measles virus. "Genome-wide associations of CD46 and IFI44L genetic variants with neutralizing antibody response to measles vaccine." (PMID 35360730, 2022). "For instance, variants in the interferon-induced protein 44 like (IFI44L) and the cluster of differentiation 46 (CD46) genes were associated with measles-specific neutralizing antibody titers in response to MMR vaccine." (PMID 35360730, 2022). "Similarly, a variant (rs1333973) affecting the exclusion of exon 2 of the antiviral gene IFI44L (modified protein, Student’s test; psQTL < 1.1 × 10−56, R2 = 0.72, SPIDEX’s Z = 3.9) is associated with measles-specific humoral immunity and increased risk of febrile seizures." (PMID 30975994, 2019).
osteosarcoma (2 papers, 2021). A usually aggressive malignant bone-forming mesenchymal neoplasm, predominantly affecting adolescents and young adults. "Compared with normal bone cells, the expression of IFI44L in osteosarcoma was decreased, and the high expression of IFI44L indicated a good prognosis in osteosarcoma patients." (PMID 34384424, 2021).
pancreatic ductal adenocarcinoma (2 papers, 2017 to 2018). An infiltrating adenocarcinoma that arises from the epithelial cells of the pancreas. "In the present study, we determined the feasibility of three genes (ERO1A, OSBPL3 and IFI44L) working as potential biomarkers in pancreatic ductal adenocarcinoma (PDAC)." (PMID 28881752, 2017).
respiratory syncytial virus infections (2 papers, 2021 to 2022). "pointed out that when influenza virus and respiratory syncytial virus infections occur, IFI44L acts as an IFN-stimulated factor regulatory gene, and its expression level increases." (PMID 35620480, 2022).
abdominal aortic aneurysm (1 paper, 2023). Enlargement and ballooning of the vessel that supplies arterial blood to the abdomen, pelvis and legs. "For example, several (5/39) of the significant genes (including LPL, IFI44L, ACKR2, HBA1, and HBA2) have also been found to be differently expressed in abdominal aortic aneurysms." (PMID 36836499, 2023).
Aortic Rupture (1 paper, 2022). The tearing or bursting of the wall along any portion of the AORTA, such as thoracic or abdominal. "OAS3, IFIT1, and IFI44L may be predictive factors for aortic rupture." (PMID 36158807, 2022).
breast carcinoma (1 paper, 2018). "Treatment of other breast cancer cells SKBR3 and BT474 by compound KDM5-C70 also induced expression of OAS2, IFI44L, and IFI44, but to a lesser extent." (PMID 30080846, 2018).
coronary artery disease (1 paper, 2021). "IFIT2, IFIT3 and IFI44L are significantly related with myocardial infarction and coronary artery disease, according to Cardiovascular Disease Knowledge Portal Project Database (cvd.hugeamp.org)." (PMID 34884921, 2021).
Cough (1 paper, 2017). A sudden, audible expulsion of air from the lungs through a partially closed glottis, preceded by inhalation. "Poly(I:C), as expected, up-regulated genes associated with inflammation, innate immunity and viral responses including CXCL11, CCL5 (chemokine (C–C motif) ligand) 5 and CXCL10, interferon-induced protein 44 like (IFI44L) in ASMCs from both healthy non-cough and chronic cough volunteers." (PMID 28842514, 2017).
cutaneous melanoma (1 paper, 2023). A primary melanoma arising from atypical melanocytes in the skin. "Among these, IFI6 and IFI44L are associated with the formation and growth of cutaneous melanoma." (PMID 36774490, 2023).
cutaneous tuberculosis (1 paper, 2021). "IFI44L could also serve as a quantitative prognostic marker for treatment response in macrophages and individuals with cutaneous tuberculosis, thereby further supporting the role of IFI44L in clearing M. tuberculosis." (PMID 34722780, 2021).
diabetic retinopathy (1 paper, 2022). "What’s more, we have discovered that high IFI44L expression seemed to have strong associations with the disease status of diabetic retinopathy according to its expression in GSE160306." (PMID 36451477, 2022).
discoid lupus erythematosus (1 paper, 2024). A chronic, autoimmune skin condition that manifests with a red, scaling rash, most often found on the face, ears, and scalp; these lesions often lead to permanent scarring and dyspigmentation. "Moreover, the methylation of IFI44L can also distinguish between discoid lupus erythematosus (DLE) and SLE." (PMID 39737399, 2024).
fungal infection (1 paper, 2025). "IFI44L may also be linked to immune dysregulation, contributing to secondary fungal infection." (PMID 39688402, 2025).
glioma (1 paper, 2021). A benign or malignant brain and spinal cord tumor that arises from glial cells (astrocytes, oligodendrocytes, ependymal cells). "Moreover, according to TCGA data, in glioma patients, higher IFI44L expression predicted higher survival probability." (PMID 34903206, 2021).
head and neck squamous cell carcinoma (1 paper, 2024). A squamous cell carcinoma that arises from any of the following anatomic sites: lip and oral cavity, nasal cavity, paranasal sinuses, pharynx, larynx, and salivary glands. "Recent studies have indicated that in head and neck squamous cell carcinoma (HNSCC) cells, the knockdown of IRF1 can reduce the expression levels of IFI44L and suppress cell proliferation and invasiveness." (PMID 39737399, 2024).
hepatic cancer (1 paper, 2018). "In this study, we successfully enriched hepatic cancer stem-like cells and first identified that overexpression of IFI44L significantly reduces the chemoresistance towards doxorubicin and knockdown of IFI44L promotes sphere formation in HCC cells." (PMID 29848298, 2018).
Hepatitis (1 paper, 2024). Inflammation of the liver. "ISGs that were more highly expressed in hepatocytes in the HBeAg‐positive infection phase than in the hepatitis phases, including IFI44, ISG15, IFI44L, MX1, and OAS3, were not correlated with ALT levels." (PMID 39135698, 2024).
Hypertension (1 paper, 2019). The presence of chronic increased pressure in the systemic arterial system. "The expression of IFI44L is demonstrably increased upon contact of Nickel or Nickel Chloride, which is associated with elevated prevalence of hypertension." (PMID 30967125, 2019).
IgA nephropathy (1 paper, 2025). "Recent studies have identified an increased expression of interferon signature genes such as IFI6, IFI44L, and IFITM3 in PBMCs of patients with IgA nephropathy." (PMID 40269956, 2025).
Immunodeficiency (1 paper, 2022). Failure of the immune system to protect the body adequately from infection, due to the absence or insufficiency of some component process or substance. "The Family with Sequence Similarity 89 Member A (FAM89A) and the Interferon Induced Protein 44 Like (IFI44L) are both protein coding genes that have been linked to a rare mild immunodeficiency (immunodeficiency 38 with basal ganglia calcification)." (PMID 35186993, 2022).
inflammatory bowel disease (1 paper, 2025). A spectrum of small and large bowel inflammatory diseases of unknown etiology. "Inflammatory bowel disease was inversely associated with GATE scores for 5 interferon-stimulated genes—IFIT1, IFI44, HERC5, MX1, IFI44L—regulated by the same trans-expression quantitative trait locus, and with the GATE score for IFNL1." (PMID 40996888, 2025).
insomnia (1 paper, 2025). A sleep disorder characterized by difficulty in falling asleep and/or remaining asleep. "Among these, IFI44, IFI44L, and IRF9, were identified as having a significant effect on diagnosing insomnia-associated uveitis." (PMID 39958336, 2025).